CD34 (CD34 molecule)
Diseases named in the same sentence as CD34 in open-access papers (continued):
Sharing a sentence is not in itself a finding about the gene and the disease.
allergic disease (5 papers, 2009 to 2025). An immune response that occurs following re-exposure to an innocuous antigen, and that requires the presence of existing antibodies against that antigen. "MC-activated mesenchymal stromal cells stimulate CD34+ cells to proliferate and to regulate their expression of early allergy-associated genes." (PMID 24381572, 2013). "Functional relevance of this observation is demonstrated by increased IL-5 and IL-13 production by CD34+ cells and expression of allergy-associated genes by these progenitor cells after interaction with MC-primed BM-MSCs." (PMID 24381572, 2013). "An additonal recent study has confirmed that CD34+ human progenitor can act as effector cells in allergy." (PMID 20066174, 2009). "To assess whether MC-activated BM-MSCs might prime progenitor cell differentiation into allergic effectors, we have examined the expression of early allergy-related genes in CD34+ progenitor cells." (PMID 24381572, 2013). "This is based largely on evidence that stem cells or CD34+ progenitor cells are recruited to the site of inflammation in allergic diseases, likely through many of the same adhesion and chemokine receptors used for stem cell homing to the bone marrow (PSGL-1, CXCL12, α4β1 integrin, CD44, etc)." (PMID 20066174, 2009). "In a prior study, CD34+ stem cells from blood donors express ST2L and produce IL-5 and IL-13 in response to IL-33 supporting these stem cells as potential effector cells in allergic diseases." (PMID 36177009, 2022).
aneurysm (5 papers, 2020 to 2025). Bulging or ballooning in an area of an artery secondary to arterial wall weakening. "Therefore, this study suggests that targeting CD34+ cell‐derived myofibroblasts may be a promising therapeutic approach aimed at stabilizing aneurysms and reducing the rupture risk." (PMID 39731355, 2025). "Functionally, our combined BMT and DTR mouse model demonstrates that the depletion of either systemic or non‐BM CD34+ cells exacerbates aneurysm progression, elucidating their essential protective role." (PMID 39731355, 2025). "This profile highlights the stem‐like properties of adventitial CD34+ cells and their capacity to differentiate in response to aneurysm signals." (PMID 39731355, 2025). "It has been proven that the levels of CD34+ cells are altered in patients with abdominal aortic aneurysms compared with patients with peripheral vascular disease, and the CD34+ cells were correlated with aneurysm diameter." (PMID 33869300, 2021). "Notably, PDGFRb deletion in CD34+ cells not only promoted AAA progression but also significantly increased the mortality rate of aneurysms." (PMID 39731355, 2025). "CD34+ cells actively contribute to the formation of a fibrous collar around the aneurysmal aorta by generating Periostin+ myofibroblasts, which may enhance the biomechanical strength to protect the aneurysm from rupture." (PMID 39731355, 2025). "In this study, we found that non‐BM‐derived CD34+ cells function as fibroblast progenitor cells to generate Periostin+ myofibroblasts, which participate in the formation of the adventitial fibrous collar of the aneurysmal aorta, thereby restricting aneurysm development." (PMID 39731355, 2025). "To determine the distribution and expression patterns of CD34 in aortic tissues, we collected samples of human thoracic aortic aneurysm (TAA) and AAA, corresponding non‐dilated aortic tissues, and Ang II‐ and CaCl2‐induced mouse aneurysm samples." (PMID 39731355, 2025). "In the in vivo study, we detected a gross lower expression level of CD68 and ARG1 (macrophage), Aggrecan (chondrocyte), OPN (osteoblast), ADIPQ (adipocytes), CD34 (mesenchymal cells), and LUM (fibroblasts) in the FAM3A-overexpressing aneurysm tissues compared with the matched Ad-sham tissues." (PMID 37660071, 2023). "The aneurysm tissues have some CD34-positive cell infiltration, while the control arteries have no significant CD34 positive cells, which prove that the characteristics of modeling aneurysms are consistent with those of normal aneurysms." (PMID 32908904, 2020). "Collectively, although both PDGFRs in CD34+ cells play important roles in CD34+ cell proliferation and AAA progression, PDGFRb, rather than PDGFRa, is required for CD34+ cell transdifferentiation into Periostin+ myofibroblasts, thereby protecting aneurysms from rupture." (PMID 39731355, 2025). "CD34-positive neovessel endothelium could not be detected in any of the aneurysms." (PMID 32681192, 2020). "Histological analysis (such as SMA-α, CD31, CD34, CD68, collagen IV, and Ki67) and the other relevant indexes were compared between the ideal model's aneurysmal tissues and the human intracranial aneurysm's tissues to confirm whether we have successfully established elastase-induced aneurysm models." (PMID 32908904, 2020).
angiomyxoma (5 papers, 2012 to 2025). A benign soft tissue neoplasm characterized by the presence of neoplastic spindle and stellate cells, and vascular proliferation in a myxoid stroma. "Superficial angiomyxoma shows prominent vasculature, neutrophil-rich stroma, a lobular growth pattern, and CD34-positive spindle cells; multiple lesions require exclusion of Carney complex." (PMID 41283480, 2025). "Aggressive angiomyxomas display myxoid stroma, thick-walled vessels, and positivity for desmin, ER/PR, and variably CD34." (PMID 40428263, 2025). "Superficial angiomyxomas are generally immunoreactive with vimentin and CD34, which was consistent with the present case." (PMID 22919399, 2012).
Arthritis (5 papers, 2010 to 2021). Inflammation of a joint. "In a rat arthritis model, synovial angiogenesis was associated with overexpression of VEGF, CD34, and HIF-1α, and the levels of HIF-1α were positively correlated with the arthritis index." (PMID 27549205, 2016). "CD34−/− mice display increased resistance to a wide variety of inflammatory diseases including allergic lung inflammation, arthritis and Salmonella infection, and CD43 has been shown to regulate TH cell migration in vivo." (PMID 23555902, 2013). "In the stromal fraction, we found a higher proportion of CD34-positive cells in samples from control patients than from arthritis patients." (PMID 20105279, 2010). "Within the CD45-negative cells, more CD34-positive cells were seen in controls than in arthritis patients." (PMID 20105279, 2010). "Modern cellular phenotyping has uncovered that a Thy1+CD34+ subset of SFs, which expresses several complement proteins intracellularly and is found in the sublining regions of the synovium, critically contributes to arthritis pathogenicity." (PMID 34068191, 2021). "Mice with humanized immune systems, namely NOD/Shi-scid/IL-2Rγnull mice reconstituted with CD34+ hematopoietic stem cells, that were infected with EBV went on to spontaneously develop erosive arthritis, suggesting a causative role of EBV in arthritis development." (PMID 34080972, 2021). "CD34-expression was higher in the control samples than in arthritis samples (P = 0.034)." (PMID 20105279, 2010).
benign fibrous histiocytoma (5 papers, 2014 to 2024). A benign neoplasm composed of fibroblastic spindle cells in a whorled storiform pattern. "Deep benign fibrous histiocytoma may also show a hemangiopericytoma-like vasculature and may express CD34." (PMID 25432794, 2014). "Benign fibrous histiocytoma may resemble DFSP, but it is usually negative for CD34 and Bcl-2." (PMID 30703718, 2019).
beta thalassemia (5 papers, 2013 to 2024). Beta-thalassemia (BT) is characterized by deficiency (Beta+) or absence (Beta0) of synthesis of the beta globin chains of hemoglobin (Hb). "The practicable therapeutic strategy for beta-thalassemia thus involves editing human-peripheral-blood-mobilized CD34+ hematopoietic stem and progenitor cells (HSPSc) by ribonucleoprotein (RNP) electroporation." (PMID 35682629, 2022). "CD34-positive cells from beta-thalassemia patients transferred with the beta-globin gene with lentiviral vector ex vivo are transplanted to refill beta-globin." (PMID 33425872, 2020). "To bridge this gap, we developed an artificially engineered model for human beta thalassemia by knocking down beta-globin gene and protein expression in cultured CD34+ cells obtained from healthy adults." (PMID 23861885, 2013). "Human CD34+ cells from healthy volunteers were cultured ex vivo for 21 days in a two-phase, serum free system to engineer a beta-thalassemia major model." (PMID 23861885, 2013).
brain injury (5 papers, 2017 to 2025). Acute and chronic (see also brain INJURIES, CHRONIC) injuries to the brain, including the cerebral hemispheres, CEREBELLUM, and brain STEM. "Electrical stimulation also increased the number of CD34+ cells and vWF+ vascular cells in the injured hippocampus, which was correlated with vascular remodeling after brain trauma." (PMID 29201537, 2017).
cardiomyopathy (5 papers, 2016 to 2025). A disease of the heart muscle or myocardium proper. "We then proceeded to compare the expression of stemness genes in different groups of cardiomyopathies using the same method, and screened for the same high expression of CD34, EPAS1, and MYC." (PMID 38799173, 2024). "A future-oriented approach could involve tailoring cell therapy based on dominant pathophysiological features, prioritizing MSCs in inflammation-driven cardiomyopathies and CD34+ cells in cases characterized by microvascular rarefaction." (PMID 40508220, 2025). "For example, MSCs may be prioritized in inflammation-driven cardiomyopathy, while CD34+ endothelial progenitor cells may be more effective in microvascular dysfunction." (PMID 40508220, 2025). "The heart tissue showed hypertrabeculation that stained with the endothelial marker CD34, implying presence of non-compaction cardiomyopathy similarly to the histopathological findings seen in some of the human MUL patients." (PMID 27044324, 2016).
chronic heart failure (5 papers, 2012 to 2024). "We therefore sought to explore a correlation between changes in galectin-3 plasma levels and response to transendocardial CD34+ cell transplantation in patients with chronic heart failure." (PMID 31885743, 2019). "In patients with chronic heart failure undergoing CD34+ cell therapy, a decrease in galectin-3 plasma levels is associated with beneficial response to this treatment modality." (PMID 31885743, 2019). "A decrease in CD45dim/CD34+/CD133+ has been inversely correlated with both aging and chronic heart failure (CHF)." (PMID 39974348, 2024). "However, the effect of high doses of CD34+ cells might be less constant in chronic heart failure (CHF) patients." (PMID 32297205, 2020).
cystic lymphangioma (5 papers, 2014 to 2025). "Therefore, CD31 and CD34 may be useful markers to discriminate between an adult pancreatic hemangioma and other types of cystic neoplasm, particularly cystic lymphangiomas." (PMID 25013478, 2014). "The predominance of CD31 positive vessels over CD34 positive ones in the inner membrane of the CSDH could be related to an attempt by the inner membrane to promote "circumscription and resorption" of the pre-existing hygroma." (PMID 36854960, 2023).
Diamond-Blackfan anemia (5 papers, 2015 to 2025). A congenital aregenerative and often macrocytic anemia with erythroblastopenia. "Specifically, mutations in RPS19 in patients with Diamond-Blackfan anemia affect proliferation and apoptosis of BM CD34+ progenitors." (PMID 36821386, 2023). "CD34+CD71lo EVs were reported as alternative indicators in the diagnosis of inherited Diamond-Blackfan anemia (DBA), as an absence of these EVs was associated with a low level of erythroid burst–forming units in DBA patients." (PMID 36106632, 2022).
eosinophilia (5 papers, 2006 to 2024). "It has been found that increased expression of IL5RA on CD34+ cells favors eosinophilopoesis and therefore may contribute to the subsequent development of blood and tissue eosinophilia, a hallmark of allergic inflammation." (PMID 23515576, 2013). "Heightened expression of IL-5Rα on CD34+ cells promotes eosinophil production, potentially contributing to the subsequent emergence of eosinophilia in both blood and tissues." (PMID 39062104, 2024). "Following the allergen challenge, there is a notable rise in the percentage of CD34+ cells that express IL-5Rα in comparison to the levels observed in the bone marrow before allergen exposure, which is followed by blood and sputum eosinophilia." (PMID 39062104, 2024). "Studies have shown that IL-33 and TSLP modulate migration of CD34+ progenitor cells in patients with asthma, further enhancing eosinophilia and basophilia, and also inversely correlate with lung function." (PMID 36311787, 2022). "The initial development of eosinophilia is induced in a complex way, including T lymphocyte independent mechanisms, as well as production of IL-5 from CD34+ cells." (PMID 16740158, 2006). "Mouse model studies suggest that eosinophilia and basophilia are promoted through TSLP-mediated upregulation of CD34+ progenitor cells and their recruitment at sites of infections." (PMID 36311787, 2022). "In this study, the transcription level of CD34 was upregulated, and XLOC_1055137, which is located in the vicinity of CD34, was downregulated at 12 hpi and 24 hpi, which may play a role in the induction of eosinophilia in the peripheral blood of infected puppies during early infection." (PMID 34277631, 2021).
Fabry disease (5 papers, 2021 to 2025). Fabry disease (FD) is a progressive, inherited, multisystemic lysosomal storage disease characterized by specific neurological, cutaneous, renal, cardiovascular, cochleo-vestibular and cerebrovascular manifestations. "In the study, five male patients with Fabry disease aged 29 to 48 years received transplantation of CD34+ genetically modified with LVs encoding GLA in a does of 3.1–13.8 × 106/kg." (PMID 36835039, 2023). "We have shown that LV‐mediated gene therapy employing autologous, peripheral blood‐mobilised CD34+ HSPCs with non‐myeloablative conditioning is a safe treatment modality in a Phase 1 cohort of five male Fabry disease patients." (PMID 39794302, 2025). "Treating patients with autologous CD34+ cells engineered to express α‐gal A continues to be a safe therapy for Fabry disease patients." (PMID 39794302, 2025). "Single-dose lentivirus transduced with α-gal A (alpha-galactosidase A) CD34+ gene therapy was also assessed in five adult males with Fabry disease." (PMID 37240368, 2023). "Three LV clinical trials have been registered for Fabry disease, all involving transplantation of CD34+ genetically modified with LVs (NCT04999059, NCT03454893, and NCT02800070)." (PMID 36835039, 2023). "The study included 120 patients with Gaucher and Fabry diseases with the aim of investigating the therapeutic effect of transplantation of autologous CD34+ HSCs (CD34+) genetically modified with a retroviral vector." (PMID 36835039, 2023). "In a pilot safety study, we have targeted enriched CD34+ hematopoietic stem/progenitor cells (HSPCs) for lentivirus (LV)-mediated gene therapy in patients with Fabry disease (NCT02800070)." (PMID 33633114, 2021). "In this pilot, single-arm study (NCT02800070), five adult males with Type 1 (classical) phenotype Fabry disease were infused with autologous lentivirus-transduced, CD34+-selected, hematopoietic stem/progenitor cells engineered to express alpha-galactosidase A (α-gal A)." (PMID 33633114, 2021). "The primary objectives of this study were to determine the safety and toxicity of autologous stem cell transplantation with mobilized CD34+ hematopoietic cells transduced with a lentiviral vector containing human codon-optimized α-gal A cDNA in adult male Fabry disease patients." (PMID 33633114, 2021). "In conclusion, NCT03454893 was an open-label clinical study aimed at assessing the autologous transplantation of CD34+ stem cells that were modified with a lentiviral vector carrying the human GLA gene in 15 patients diagnosed with Fabry disease (FD)." (PMID 39684857, 2024).
follicular lymphoma (5 papers, 2013 to 2025). Follicular lymphoma is a form of non-Hodgkin lymphoma characterized by a proliferation of B cells whose nodular structure of follicular architecture is preserved. "In another study, clonal CD34+CD19+ progenitors were detected in bone marrow of BCL2-IgH-positive follicular lymphoma patients." (PMID 32010428, 2020). "Irradiated newborn NOD-SCID-gamma (NSG) mice that had received an intrahepatic injection of human CD34+ stem cells, were inoculated s.c. with 2.5 × 106 human RL follicular lymphoma cells." (PMID 30143632, 2018). "The lack of CD34 or TdT expression exclude a precursor lesion, and hence indicate a mature B-cell type while staining for CD10 indicates a follicular lymphoma of germinal center origin." (PMID 39787145, 2025).
Granuloma (5 papers, 2014 to 2025). A compact, organized collection of mature mononuclear phagocytes, which may be but is not necessarily accompanied by accessory features such as necrosis. "Consistent with our TEM findings, there was marked and dominant immunolabeling for CD34 cells in the granuloma peripheral zone and, as expected, in vascular endothelial cells because CD34 is also expressed by these cells." (PMID 40498832, 2025). "We then evaluated the presence and distribution of CD34 cells within granulomas." (PMID 40498832, 2025). "In one case of amalgam tattoos, granulomas around metallic material and repair features were present, inducing activation of the CD34+ stromal cells, which suggests that these cells may transform into fibroblasts and myofibroblasts." (PMID 25266164, 2014). "Compared to control samples, granuloma-remote CS parenchyma is characterized by significantly increased expression of HLA-DR, Treg markers FOXP3, CD25 and GITR, endothelial/stem-cell marker CD34, and global nuclei/proliferation marker Histone-H3." (PMID 38766184, 2024). "Perivascular and interstitial CD34+SCs/TCs are usually absent in large inflammatory infiltrates and in granulomas but present around them." (PMID 34298962, 2021). "However, the absence of granulomas on bone marrow histology and the presence of monocytic proliferation and CD34+/CD117+ blasts pointed toward CMML." (PMID 40502875, 2025).
head and neck squamous cell carcinoma (5 papers, 2003 to 2023). A squamous cell carcinoma that arises from any of the following anatomic sites: lip and oral cavity, nasal cavity, paranasal sinuses, pharynx, larynx, and salivary glands. "In present study, we did observe a positive association between HIF-1α expression and CD34 Chalkey count of primary tumor vascularity similar to a report for head and neck squamous cell carcinoma patients." (PMID 24165149, 2013). "Vitamin D3 combined with various cytokines induced the differentiation of CD34+ progenitors isolated from patients with head and neck squamous cell carcinoma (HNSCC), resulting in increased numbers of cells phenotypically similar to mature DCs." (PMID 37006306, 2023). "In patients with head and neck squamous cell carcinoma, an increased number of CD34+ progenitor cells endowed with natural suppressor activity is present in the peripheral blood and within the tumour tissue." (PMID 14562018, 2003).